HOXA1 (homeobox A1)
Diseases named in the same sentence as HOXA1 in open-access papers (continued):
Sharing a sentence is not in itself a finding about the gene and the disease.
tumor (continued). "The specific mechanism may be that HOTAIRM1 can enhance the expression of HOXA1 in MDSCs and high levels of HOXA1 can delay tumor progression and enhance the antitumor immune response by downregulating the immunosuppression mediated by MDSCs." (PMID 32005273, 2020). "In addition, increased expression of HOXA1 has been shown to reduce tumor growth, decrease the percentage of MDSCs, and enhance the immune response in a tumor mouse model." (PMID 31404149, 2019). "Moreover, HOXA1 knockdown significantly inhibited overall tumor growth as assessed by the measurements of tumor volume and mass (P < 0.05 and P < 0.01, respectively)." (PMID 26791264, 2016). "It was shown that miR-10a could be involved in the tumor invasiveness through HOXA1 suppression in PDAC." (PMID 27137215, 2016). "Moreover, knockdown of HOXA1 expression also led to a significant reduction in xenograft tumor formation." (PMID 26791264, 2016). "Second, knockdown of HOXA1 expression in GC cells not only inhibited cell proliferation, migration, and invasion and induced changes in the cell cycle in vitro but also suppressed xenograft tumor formation." (PMID 26791264, 2016). "Our findings indicate that HOXA1 may contribute to oral carcinogenesis by increasing tumor cell proliferation, and suggest that HOXA1 expression might be helpful as a prognostic marker for patients with OSCC." (PMID 22498108, 2012). "Our data revealed that miR-202-3p elevation suppressed the tumor growth of HepG2 cell xenografted into nude mice, as reflected by reduced tumor weight and volume in nude mice injected with miR-202-3p, which the addition of oe-HOXA1 could reverse this effect." (PMID 33520978, 2020). "In addition, overexpression of HOXA1 could reduce the immunosuppression of MDSCs and delay tumor progression." (PMID 29662483, 2018). "We found that methyl groups gather more often in a specific region of HOXA1, named 3′UTR, in tumor cells compared to healthy tissues." (PMID 38473236, 2024). "HOXA1, HOXA2, HOXA3, and HOXA10 had high expression in GBM tumor tissues compared to normal tissues." (PMID 37351805, 2023). "The methylation of HOXA1, IGFBP2, PTX3, TIMP1, SHOX2, and SH2D4A decreases with increasing tumor grade." (PMID 37091145, 2023). "Studies have shown that HOXA1 plays a key role in regulating the cell cycle, promoting EMT, and enhancing tumor cell proliferation, migration, and invasion." (PMID 37854681, 2023). "Univariate and multivariate analyses revealed that HOXA1, HOXA6 expression and tumor grade, age, primary therapy outcome and age were independent factors affecting the prognosis of LGG patients." (PMID 35349479, 2022). "LncRNA HotairM1 can recruit EZH2 and SUZ12 to the promoter of its target gene HOXA1, leading to histone H3K27 trimethylation and epigenetic silencing of HOXA1, promoting CSC self-renewal and tumor proliferation." (PMID 36437919, 2022). "Homeobox A1 (HOXA1), an oncogene motivating tumor growth and tumor motility by regulating the expression of downstream pro-migration and pro-invasion genes, cyclin D1 (CCND1), MET, smoothened (SMO), and semaphorin 3C (SEMA3C)." (PMID 33917233, 2021). "HOTAIRM1 enhances the expression of HOXA1 in MDSCs and high levels of HOXA1, the target gene of HOTAIRM1, delays tumor progression and enhances the antitumor immune response by downregulating the immunosuppression of MDSCs." (PMID 34295338, 2021). "HOXA1 belongs to the Hox gene family and comprises the cluster on chromosome 7 to coordinate the development of various cell behavior patterns during embryogenesis, and abnormal expression of HOXA1 in differentiated cells may lead to the acquisition of tumor-promoting properties." (PMID 34180753, 2021). "Collectively, the experimental data demonstrated that miR-202-3p harbored tumor-suppressive properties during the development and progression of HCC through the KDM3A/HOXA1/MEIS3 axis in vitro and in vivo." (PMID 33520978, 2020).
tumor (continued). "For instance, it has been shown that the KDM3B gene exhibits potential tumor-suppressive activity in AML and it transcriptionally regulates HOXA1 via retinoic acid response elements." (PMID 31426381, 2019). "The recurrent tumour showed a 70–80 fold increase of expression of transcription factors ASCL1 and HOXA1 and tyrosine kinases FGFR3, HER3, HER4 and MET." (PMID 31747973, 2019). "Highly expressed in many types of tumor cells, HOXA1 (Homeobox A1) is a DNA-binding protein and involved in facilitating cell proliferation, invasion, metastasis, and tumor progression." (PMID 28893210, 2017). "For example, HOXA1 was shown to be an independent prognostic factor in an OSCC cohort, and was also related with T stage, N stage, tumor differentiation and proliferative potential." (PMID 26041877, 2015). "In this study, we investigated 18 CpG sites along the HOXA1 gene and found five differentially methylated sites between OSCC and adjacent normal tissue, all of them located in the 3′UTR and body of the gene and with hypermethylation in tumor samples." (PMID 38473236, 2024). "For HOXA1, no significant age-related differences were observed (P=0.4329), but significant differences were found in tumor size, histology, clinical stage, ER status, and BRCA1 status." (PMID 39267845, 2024). "Based on bioinformatics analysis utilizing gene co-expression network analysis, evidence suggests a negative correlation between the expression levels of HOXA1 and the survival prognosis of the tumor, implying a significant role in HNSCC development." (PMID 38311789, 2024). "Moreover, the involvement of HOXA1 and HOTAIRM1 in promoting tumor development in vivo was validated." (PMID 37854681, 2023). "In both tumor sets, some samples showed H3K27me3 enrichment along the entire length of the HOXA and HOXD clusters, but others demonstrated variability in H3K27me3 at the HOXA1 through HOXA7 loci and the proximal HOXD locus." (PMID 36759899, 2023). "Additionally, the multivariate analyses revealed that HOXA1, HOXA6 expression and tumor grade, age, primary therapy outcome and age were independent factors affecting the prognosis of LGG patients." (PMID 35349479, 2022). "Mouse tumor tissues were subject to qRT-PCR and Western blot analysis, and the results demonstrated that the miR-202-3p agomir diminished the protein expression of KDM3A, HOXA1, and MEIS3 in nude mice." (PMID 33520978, 2020). "However, several issues in this investigation remain to be resolved, such as the exact regulatory mechanism of HOTAIRM1/HOXA1 in MDSC function and the factors that induce the downregulation of HOTAIRM1 in MDSCs under tumor conditions." (PMID 29662483, 2018). "Taken together, downregulation of HOXA1 mediates, at least in part, the tumor-suppressing effect of miR-100 but not its EMT-inducing function." (PMID 24586203, 2014). "Additionally, some other loci showing significant differences in DNA methylation levels between tumor and non-tumor lung tissue have been identified, including: CDKN2A EX2, CDX2, HOXA1, SFPR1, and TWIST1 gene." (PMID 23086271, 2013). "The expression of HOXA1 was not correlated with age, gender, ethnicity, tumor localization, alcohol or tobacco consumption, location of the tumor, and vascular or neural infiltration." (PMID 22498108, 2012). "HOXA1 expression was not significantly correlated to HER2 tumor status in any of the datasets." (PMID 34490074, 2021). "While this work was in preparation, three new miR-210 targets were validated, i.e. HOXA1, HOXA9 and FGFRL1, and the analysis of tumour xenografts derived from cancer cell lines overexpressing miR-210 suggested a potential involvement of miR-210 in tumour growth initiation." (PMID 20436681, 2010).
tumor (continued). "Finally, it was confirmed that HOTAIRM1 could enhance the expression of HOXA1 in MDSCs and that high levels of HOXA1, the target gene of HOTAIRM1, could delay tumor progression and enhance the antitumor immune response by downregulating the immunosuppression of MDSCs." (PMID 29662483, 2018).
cancer (49 papers, 2007 to 2025). A tumor composed of atypical neoplastic, often pleomorphic cells that invade other tissues. "In many cancers, upregulation of HoxA1 has been associated with the suppression of apoptosis via upregulation of the anti-apoptotic genes Bcl2 and BAX, and the promotion of proliferation via upregulation of Cyclin D128,29." (PMID 38365890, 2024). "HOXA1 de novo or overexpression appears systematically associated with cancer progression and poor prognosis." (PMID 34490074, 2021). "HOXA1 has been shown to promote cell proliferation in adult hematopoietic stem cells and in various cancer cells." (PMID 40076953, 2025). "In carcinoma cell lines, HOXA1 regulates cell proliferation by various mechanisms depending on the cell line used." (PMID 40076953, 2025). "The broad expression and notable prognostic significance of HOXA1-4 genes have been observed across various human cancers." (PMID 38311789, 2024). "Numerous studies have consistently shown that the activation of HOXA1-4 genes can drive cancer progression." (PMID 38311789, 2024). "HOXA1 overexpression promotes apoptosis and enhances the chemosensitivity of cancer cells, whereas the inhibition of HOXA1 has the opposite effect." (PMID 38203731, 2023). "HOXA1 is highly expressed in several types of cancer, including breast cancer, oral squamous cell carcinoma, hepatocellular carcinoma, and gastric cancer, and is associated with a poor prognosis." (PMID 37854681, 2023). "Previous studies have reported that HOXA1 contributes to cancer pathogenesis and progression, immunosuppressive activity of myeloid-derived suppressor cells, and therapeutic response." (PMID 35223488, 2022). "In this study, we found that HOXA1 has potential to serve as a radioresistance-predictive biomarker in multiple cancer types." (PMID 36119466, 2022). "Mechanistically, HOXA1 affected radiosensitivity via regulation of the DNA repair capacity of cancer cells." (PMID 36119466, 2022). "In this study, we identified HOXA1 as a new intrinsic radioresistance marker of multiple cancer types." (PMID 36119466, 2022). "HOXA1 expression is extremely low during normal growth and differentiation but is detectable in a variety of human cancer lesions." (PMID 36119466, 2022). "In the present study, we propose HOXA1 as a candidate biomarker of intrinsic radioresistance in multiple cancer types." (PMID 36119466, 2022). "This supports the contribution of HOXA1 in cancer aggressiveness and thereby reinforces its critical role in breast oncogenesis." (PMID 34490074, 2021). "HOXA1 activity would result in conferring gene expression profiles and cell properties similar to ER− cancers." (PMID 34490074, 2021). "Bioinformatic analysis showed that, among the 2,555 genes shared by the HOXA1 and ERα-associated mRNA expression profiles, about half is upregulated in the presence of HOXA1 but downregulated in ER+ cancers, while the other half shows the opposite correlation." (PMID 34490074, 2021). "The inhibition HOXA1 exerts on ERα can define one modality of HOXA1 action resulting in cancer aggressiveness." (PMID 34490074, 2021). "In the results of our HNSCC IHC, the expression of HOXA1, which is mainly located in the cell nucleus, is extremely low in adjacent normal tissues while it is widely distributed in cancer nest." (PMID 33763449, 2020). "HOXA1 protein immunostaining was mainly found in the cell nucleus but widely distributed in cancer nest." (PMID 33763449, 2020). "For example, HOXA1 has been found to induce tumorigenesis in multiple types of cancers such as breast, lung, and gastric cancers 15-18." (PMID 32284737, 2020). "Remarkably, USP22 knockout had pronounced effects on expression of these important cancer-associated gene sets such as c-Myc, E2F, and selected genes including ALDH1A3, CCNE1/G1, E2F6, HOXA1, MMP9, NFKB2, TP63, TPM4, SET7/9 were validated by qRT–PCR." (PMID 31842906, 2019).
cancer (continued). "Another important experiment indicated that upregulation of HOXA1 activated the transcription of cyclin D1 and promoted the G1-S transition in cancer cells." (PMID 26791264, 2016). "MNI identified HoxA1 (homeobox A1) as the top candidate, and subsequent experimental work showed that in vitro silencing of HoxA1 can revert the cancer phenotype." (PMID 28035989, 2016). "HOXA1 was obviously upregulated in 54.5 % (144/264) of the primary cancer specimens, whereas HOXA1 was upregulated in only 23.1 % (61/264) of adjacent normal mucosae." (PMID 26791264, 2016). "Among other candidates, the transcription factor HOXA1 was found to be significantly overexpressed during cancer progression." (PMID 25927933, 2014). "Since HOXA1 is expressed in a number of cancers, our findings encourage its verification and monitoring in other malignancies." (PMID 22498108, 2012). "The misexpression of homeobox transcription factor genes has also been reported in cancer tissues; for example, HOXA1 and Six1 transform mammary epithelial cells, and Msx1 and Cdx transform myoblasts and intestinal epithelial cells, respectively." (PMID 21600039, 2011). "Five cancer samples showed DNA methylation of HOXA1, while only one AdjNTL sample was methylated at this locus." (PMID 17967182, 2007). "Furthermore, HOXA1 interacts with PITX2, increasing its activity levels and thereby promoting lysosomal exocytosis‐mediated SASP associated with cancer aggressiveness." (PMID 40995693, 2025). "In cancer cells, HOXA1 plays a critical role in cell migration and proliferation." (PMID 40076953, 2025). "Additionally, we explored the utility of HOXA1-4 genes as biomarkers for monitoring cancer recurrence and metastasis." (PMID 38311789, 2024). "In the context of cancer research, upregulation of HOXA1 has been observed in BC." (PMID 38311789, 2024). "The misexpression of HOXA1 in differentiated cells could turn it into an oncogene to participate in cancer development." (PMID 39483475, 2024). "Furthermore, HOXA1 knockdown inhibited cancer progression, thereby confirming HOXA1 to be an oncogene." (PMID 37854681, 2023). "Interestingly, HOXA1 expression is dysregulated in several types of cancer, such as gastric, prostate, breast and hepatocellular carcinoma, and promotes cancer progression." (PMID 36766779, 2023). "Mechanistically, HOXA1 could regulate radiosensitivity via effects on the DNA repair capacity of cancer cells." (PMID 36119466, 2022). "Few studies have reported that HOXA1 regulates the radiosensitivity of cancer cells." (PMID 36119466, 2022). "This suggests that the overlapping DEGs could be key downstream genes of HOXA1 that affect the radiosensitivity of cancer cells." (PMID 36119466, 2022). "Our results suggest that HOXA1 could be used to predict radioresistance and guide individualized treatment in multiple cancer types." (PMID 36119466, 2022). "Taken together, these results suggest that high HOXA1 expression could serve as a biomarker for poor prognosis in several cancers, and that the prognostic significance of HOXA1 expression depended on the cancer type." (PMID 36119466, 2022). "Nevertheless, the mechanism underlying the upregulation of HOXA1 in cancer cells was not completely clear." (PMID 36119466, 2022). "In addition, many studies have reported that HOXA1 promoted proliferation and invasion of different cancer types." (PMID 36119466, 2022). "This confirmed that HOXA1 enhanced radioresistance of cancer cells." (PMID 36119466, 2022). "Moreover, we analyzed the prognostic value of HOXA1 expression in different human cancers using TCGA data." (PMID 36119466, 2022). "Here we summarize Non-coding genes act as regulators of HOXA1 in cancers." (PMID 33763449, 2020).